TCEA1 (transcription elongation factor A1)
Description:
Necessary for efficient RNA polymerase II transcription elongation past template-encoded arresting sites. The arresting sites in DNA have the property of trapping a certain fraction of elongating RNA polymerases that pass through, resulting in locked ternary complexes. Cleavage of the nascent transcript by S-II allows the resumption of elongation from the new 3'-terminus.
Synonyms: GTF2S; TFIIS; SII; TF2S; TCEA
Tractability: Small molecule: a structure with a bound ligand is known. PROTAC: UniProt records ubiquitination sites on it; ubiquitination databases record sites on it; its protein half-life has been measured.
Gene: Protein-coding gene on chromosome 8 (53,966,552 to 54,022,448, reverse strand). Ensembl gene ENSG00000187735.
Subcellular location: Nucleus
Subcellular location (Human Protein Atlas): Nucleoplasm; Nucleoli
Pathways (Reactome):
Disease: Formation of HIV elongation complex in the absence of HIV Tat; Formation of HIV-1 elongation complex containing HIV-1 Tat; HIV elongation arrest and recovery; Pausing and recovery of HIV elongation; Pausing and recovery of Tat-mediated HIV elongation; Tat-mediated HIV elongation arrest and recovery; Tat-mediated elongation of the HIV-1 transcript
DNA Repair: Dual incision in TC-NER; Formation of TC-NER Pre-Incision Complex; Gap-filling DNA repair synthesis and ligation in TC-NER; Transcription-Coupled Nucleotide Excision Repair (TC-NER)
Gene expression (Transcription): Formation of RNA Pol II elongation complex; RNA Polymerase II Pre-transcription Events; RNA Polymerase II Transcription Elongation
Gene Ontology:
Molecular function: protein binding; transcription elongation factor activity; nucleic acid binding; zinc ion binding
Biological process: transcription elongation by RNA polymerase II; DNA-templated transcription
Cellular component: nucleoplasm; transcription factor TFIID complex; nucleus
Genetic constraint (gnomAD): Loss-of-function variants: 12 observed, 20.75 expected, observed/expected ratio (o/e) 0.58, 90% interval 0.37 to 0.94. The upper end of that interval is the gene's LOEUF score, 0.94, which puts it in group 3 of 6, group 1 being the genes least tolerant of losing a copy. Missense variants: 175 observed, 234.82 expected, observed/expected ratio (o/e) 0.75, 90% interval 0.66 to 0.85. Synonymous variants: 67 observed, 75.9 expected, observed/expected ratio (o/e) 0.88, 90% interval 0.72 to 1.08.
Homologues: Orthologues: macaque TCEA1 (100% identical), chimpanzee TCEA1 (98% identical), mouse Tcea1 (97% identical), rat Tcea1 (97% identical), rat Tcea1l1 (97% identical), pig TCEA1 (96% identical), dog TCEA1 (93% identical), guinea pig TCEA1 (90% identical), tropical clawed frog tcea1 (77% identical), zebrafish tcea1 (77% identical). Paralogues in human: TCEA2 (65% identical), TCEA3 (59% identical), TCEANC (33% identical).
Diseases named in the same sentence as TCEA1 in open-access papers:
TCEA1 is named in the same sentence as 10 diseases in open-access papers, as found by Europe PMC text mining. Sharing a sentence is not in itself a finding about the gene and the disease. The quoted sentences say what the papers report.
hepatocellular carcinoma (2 papers, 2019 to 2023). A malignant tumor that arises from hepatocytes. "The DDX3X protein is stabilized by TCEA1, which promotes hepatocellular carcinoma cell proliferation and colony formation." (PMID 31906196, 2019). "The role of the YEATS4/TCEA1/DDX3 axis in hepatocellular carcinoma progression has been explored." (PMID 31906196, 2019). "TCEA1, an isoform of transcription factor SOX, is overexpressed in hepatocellular carcinoma." (PMID 37435030, 2023).
retinoblastoma (2 papers, 2020 to 2021). A malignant tumor that originates in the nuclear layer of the retina. "Our previous study has demonstrated lncRNA GAU1 could recruit Transcription Elongation Factor A1 (TCEA1) to the promoter of Polypeptide N-Acetylgalactosaminyltransferase 8 (GALNT8), thereby upregulate an oncogene expression and accelerate tumorigenesis of retinoblastoma." (PMID 32669100, 2020).
hepatic (1 paper, 2022). "The expression of Rbbp4, Tcea1, and ILF2 were significantly downregulated in significant hepatic-steatosis NAFLD patients compared to non-significant hepatic-steatosis controls." (PMID 35637971, 2022).
liver cancer (1 paper, 2023). An epithelial or non-epithelial malignant neoplasm that arises from the liver. "Moreover, YEATS4 can bind and activate transcriptional elongation factor A1 (TCEA1), which then promotes the upregulation of DDX3, a DEAD-box family RNA helicase with multiple cellular functions that plays an important role in liver cancer." (PMID 37435030, 2023).
lung adenocarcinoma (1 paper, 2018). A carcinoma that arises from the lung and is characterized by the presence of malignant glandular epithelial cells. "Of these, 18 could be tested in the TCGA expression data for lung adenocarcinoma, and 3 met only nominal significance (logrank test p-value < 0.05): NARS (p = 0.03), an eQTL target gene in lung, as well as ZNF426 (p = 0.02), and TCEA1 (p = 0.023)." (PMID 29335598, 2018).
ovarian carcinoma (1 paper, 2025). A malignant neoplasm originating from the surface ovarian epithelium. "Similarly, regulators of RNA processing and splicing such as TCEA1, SF3B6, ZCRB1, PNO1, and DCAF13 were overexpressed, indicating dysregulation of mRNA metabolism and splicing fidelity in ovarian cancer." (PMID 41228302, 2025).
steatosis (1 paper, 2022). Increased lipid within the cytoplasm of cells. "In contrast, overexpression of Tcea1, Rbbp4, and ILF2, respectively, could ameliorate hepatocyte steatosis." (PMID 35637971, 2022).
cancer (4 papers, 2014 to 2023). A tumor composed of atypical neoplastic, often pleomorphic cells that invade other tissues. "Importantly, GAS41 has been found to target downstream regulators such as Zinc finger E-box-binding homeobox 1 (ZEB1), transforming acidic coiled-coil 1 (TACC), and (Transcription elongation factor A protein 1) TCEA1 to modulate cancer progression." (PMID 37853482, 2023).
tumor (3 papers, 2021 to 2025). "Our previous researches showed that the aberrant open chromatin status at chr12p13.3 induces a novel cheRNA GAU1 and cis activates the expression of oncogene GALNT8 by recruiting the transcription elongation factor TCEA1, which accelerates tumor progression." (PMID 33937246, 2021).
TCEA1 also shares sentences with these, for which no sentence is quoted: gynecological cancers (1 paper).